INS (insulin)
Diseases named in the same sentence as INS in open-access papers (continued):
Sharing a sentence is not in itself a finding about the gene and the disease.
type 1 diabetes (continued). "Administration of autologous, expanded CD4+CD25highCD127low Tregs to children within 2 months of type 1 diabetes diagnosis significantly increased pTreg frequency, coinciding with a decrease in dependency on exogenous insulin." (PMID 28770318, 2017). "Autoreactive CD8+ and CD4+ T cells have been assigned independent key roles in the destruction of insulin-producing beta cells resulting in type 1 diabetes." (PMID 29403481, 2017). "Several studies have been conducted in type 1 diabetes patients where MSCs derived from adipose tissue, Wharton’s jelly, or bone marrow, either differentiated into insulin-producing cells or undifferentiated, were given to the patients." (PMID 28701182, 2017). "Increased circulating proinsulin/insulin or proinsulin/C-peptide ratios have been used as an indicator of β cell ER stress in individuals progressing to type 1 diabetes." (PMID 28951826, 2017). "Participants are youths (6–21 years) or adults (>21 years) with type 1 diabetes treated with insulin pump therapy and suboptimal glycaemic control (glycated haemoglobin (HbA1c) ≥7.5% (58 mmol/mol) and ≤10% (86 mmol/mol))." (PMID 28710224, 2017). "The metabolic and hormonal effects of two different CHO supplementation approaches during exercise in patients with type 1 diabetes under identical insulin levels were compared in this study: glucose-fructose co-ingestion (GLUFRU) and glucose alone (GLU)." (PMID 28230765, 2017). "Hyperglycemic condition in type I diabetes is controlled by administering exogenous insulin via subcutaneous route." (PMID 29387011, 2017). "Type 1 diabetes is an autoimmune disease in which insulin-producing β-cells are destroyed by CD4+ and CD8+ T cells and CAMφs." (PMID 29249872, 2017). "In clinical trials, EL was high in placentas from the type I diabetes patients, who obviously required insulin." (PMID 28587267, 2017). "Type 1 diabetes is an autoimmune disease that destroys insulin-producing beta cells in the pancreas." (PMID 28832685, 2017). "Type 1 diabetes is typically described as an immune-mediated disease in which T cells drive the specific destruction of pancreatic insulin-producing beta cells." (PMID 28770323, 2017). "While a high dose of STZ potently impairs insulin secretion mimicking type 1 diabetes, low doses are known to induce a mild impairment of insulin secretion resembling the clinical features of T2DM." (PMID 28862678, 2017). "Our findings demonstrate that social media can be used as an Internet tool for treatment of type 1 diabetes patients on the insulin pump as a part of traditional clinic visits." (PMID 30291064, 2017). "Type 1 diabetes develops as a result of the immune-mediated destruction of insulin-secreting beta cells in the islets of Langerhans of the pancreas." (PMID 28213757, 2017). "The reduction in hypoglycaemic burden in our study was almost identical to that in Russell and colleagues' study, which compared 5 day use of a bihormonal (insulin and glucagon) closed-loop system with usual pump therapy in adults with type 1 diabetes." (PMID 28094136, 2017). "The addition of pramlintide to insulin therapy in patients with type 1 diabetes improves glycemic control and reduces insulin requirement and body weight while bringing transient hypoglycemia and digestive disorders." (PMID 29029531, 2017). "To conclude, day-and-night closed-loop insulin delivery in adults with type 1 diabetes and HbA1c below 7·5% significantly improved glycaemic control while reducing the risk of hypoglycaemia." (PMID 28094136, 2017). "Evidence of insulitis has been reported in histological pancreas specimens from donors with recent-onset type 1 diabetes, along with a marked reduction in islets that stain positively for insulin compared with specimens from healthy controls." (PMID 28213757, 2017).
type 1 diabetes (continued). "The first study to evaluate the short-term outpatient use of a bi-hormonal closed-loop system in adults with type 1 diabetes applying more aggressive insulin dosing showed lower mean glucose level and hypoglycaemia risk during the 5-day study period." (PMID 28114938, 2017). "Successively, evidence has been reported of single cells in the pancreas of one healthy subject, containing both zymogen and insulin resembling granules, and of acinar cells in two individuals with type 1 diabetes with also glucagon granules." (PMID 28617859, 2017). "Insulin is a hormone for Type 1 diabetes treatment, the rationale for AD treatment is that brain areas affected in AD patients show decrease in the concentration of insulin and increase in the number of insulin receptors." (PMID 28720101, 2017). "A model of type 1 diabetes was induced by streptozotocin (STZ) treatment, which is characterized by a nearly total loss of insulin producing beta cells, insulin secretion and significantly increased blood glucose concentrations." (PMID 28837063, 2017). "Preliminary results from trials in type 1 diabetes patients indicate that hAAT was safe and well-tolerated in pediatric subjects, and improved β-cell function reducing the need for insulin after hAAT treatment in recently diagnosed patients." (PMID 28235038, 2017). "This approach allows us to leverage recent advances in the simulation of the glucose-insulin metabolism as well as new behavioral models of type 1 diabetes patients to assess the clinical impact of inaccurate glucose meters in everyday use." (PMID 28569076, 2017). "Our current study successfully developed a chitosan matrix-enhanced one-step procedure to differentiate ADSC from pig dorsal subcutaneous fat depots into high glucose-responsive insulin-secreting clusters, which have potential to ameliorate Type 1 diabetes." (PMID 28253305, 2017). "Type 1 diabetes is an autoimmune disease where the insulin-producing β-cells in the pancreas are destroyed leading to a life-long external insulin dependency." (PMID 28976992, 2017). "The pathophysiology of Type 1 Diabetes Mellitus (T1DM) is the result of autoimmune destruction of insulin-producing beta cells in the pancreas." (PMID 28968432, 2017). "Type 1 diabetes is an autoimmune disease that destroys pancreatic beta cells and typically renders the body unable to produce insulin." (PMID 28448498, 2017). "Type 1 diabetes (T1D) is an autoimmune disease characterized by T-cell–mediated destruction of insulin-producing β–cells." (PMID 29041943, 2017). "There are subtle clinical pointers that pregnancy is related to either β-cell regeneration or neogenesis in women with type 1 diabetes having increased endogenous bioactive insulin secretion." (PMID 28090333, 2017). "Unfortunately, we had insufficient power for separate analyses of diabetes type 1 and different insulin analogues." (PMID 28076434, 2017). "We retrospectively analysed data from a multicentre randomized control trial involving 32 adults with type 1 diabetes receiving day‐and‐night closed‐loop insulin delivery and sensor‐augmented pump therapy over 12 weeks." (PMID 28371223, 2017). "Immune-mediated diabetes often involves the presence of one or more autoantibodies, such as islet-cell antibodies, insulin autoantibodies, and glutamate decarboxylase-65 antibodies." (PMID 28758131, 2017). "Type 1 diabetes is an autoimmune disease arising from the destruction of pancreatic insulin-producing beta cells." (PMID 28770323, 2017). "Type 1 diabetes (T1D) is a chronic immune-mediated disease resulting from selective destruction of insulin-producing pancreatic islet β cells." (PMID 28738846, 2017). "The service is also very beneficial for people with Type-1 diabetes who need constant care in cases of sudden increase or decrease in their blood glucose levels due to any negligence in diet or insulin dose administration by the patient." (PMID 28811807, 2017).
type 1 diabetes (continued). "Antibodies specific to oxPTM-insulin (oxPTM-INS-Ab) are present in most newly diagnosed individuals with type 1 diabetes and are more common than autoantibodies to native insulin." (PMID 28526919, 2017). "Precursors to insulin-producing cells seem to have better potential to arrest autoimmune response in type 1 diabetes when administered before the onset of the disease in NOD mice." (PMID 28701182, 2017). "We found that antibodies specific to oxidative post-translationally modified insulin (oxPTM-INS) are present in the majority of newly diagnosed individuals with type 1 diabetes and are significantly more abundant than autoantibodies to native insulin (NT-INS)." (PMID 28526919, 2017). "The present study differs from the earlier study because it involves outpatients with type 1 diabetes and employed insulin degludec as basal insulin." (PMID 28683068, 2017). "In this multicentre, open-label, randomised controlled trial, we recruited women aged 18–40 years with type 1 diabetes for a minimum of 12 months who were receiving intensive insulin therapy." (PMID 28923465, 2017). "In people with type 1 diabetes, hormone responses and the accompanying effects on blood glucose levels are impaired because of autoimmune destruction of insulin-producing β-cells, resulting in a mismatch in Ra and Rd." (PMID 28662684, 2017). "Islet transplantation offers an alternative treatment for patients with type 1 diabetes, especially for those with hypoglycaemic unawareness following insulin administration." (PMID 27704164, 2017). "We aim to assess the efficacy and safety of pramlintide plus insulin therapy in patients with type 1 diabetes." (PMID 29029531, 2017). "Here we report the results of the lipoprotein particle and related lipid analyses by cohort (type 1 diabetes, type 2 insulin naïve, or type 2 previously on insulin) and treatment (insulin glargine or BIL) at baseline and follow-up." (PMID 28587667, 2017). "Insulin pumps represent the most intensive of all regimens in type 1 diabetes since insulin is continuously administered subcutaneously via the equipment." (PMID 28489876, 2017). "In fact, one recent clinical trial in 161 adults with type 1 diabetes treated with multiple daily insulin injections showed continuous glucose monitoring resulted in better glycemic control compared with conventional treatment." (PMID 28851965, 2017). "More than half of individuals were female (55%), 15.6% had type 1 diabetes, 37.5% used insulin, and over half of the population (52.1%) had been active on Livongo for 4 or more months at the time of the analysis." (PMID 28698167, 2017). "A diagnosis of type 1 diabetes was assigned on the basis of insulin need, HbA1c and islet autoantibodies." (PMID 28835984, 2017). "Islet autoantibodies, used as markers for the autoimmune destruction of insulin producing β cells, plays an essential role in predicting and diagnosing type 1 diabetes (T1D)." (PMID 29487479, 2017). "Type 1 diabetes (T1D) is a chronic inflammatory disease that is characterized by autoimmune destruction of insulin-producing pancreatic beta cells." (PMID 28877242, 2017). "In patients with longstanding type 1 diabetes, blunting of the glucagon response comes along with the disappearing endogenous insulin production, rendering the patients increasingly dependent upon epinephrine as protection against hypoglycemia." (PMID 28928674, 2017). "In type 1 diabetes the insulin-producing β cells in pancreatic islets are destroyed by the immune system, resulting in a lifelong dependence on supplemental insulin therapy and reduced life expectancy." (PMID 29497709, 2017). "10–15% have type 1 diabetes, where the immune system selectively targets insulin-producing pancreatic β cells." (PMID 28951826, 2017).
type 1 diabetes (continued). "An artificial pancreas (AP) computes the optimal insulin dose to be infused through an insulin pump in people with Type 1 Diabetes (T1D) based on information received from a continuous glucose monitoring (CGM) sensor." (PMID 28272368, 2017). "Type 1 diabetes, also called insulin-dependent DM, is generally a result of destruction of insulin-producing β cells by the immune system." (PMID 28758131, 2017). "Since the first trials in the 1970s, continuous subcutaneous insulin infusions delivered via insulin pumps have been used in patients with type 1 diabetes, and it is well established that DKA can occur as a complication of pump failure." (PMID 28659865, 2017). "National and international clinical guideline recommendations in type 1 diabetes in pregnancy should be revised to recommend offering CGM to pregnant women with type 1 diabetes using intensive insulin therapy in the first trimester." (PMID 28923465, 2017). "Regular physical activity is a fundamental part of type 1 diabetes management recommendations and has a positive impact on cardiovascular health, insulin requirement, body fitness and general wellbeing." (PMID 28840263, 2017). "These PILC secreted insulin in response to high glucose levels and have potential to provide a better biomaterial for amelioration of type 1 diabetes." (PMID 28253305, 2017). "Twelve studies investigated glycaemic control whereas few studies were found that investigated SES in relation to SMBG, insulin regimens or access to specialist healthcare in relation to adults with type 1 diabetes." (PMID 28489876, 2017). "An intriguing result from the differential expression pathway analysis was the perturbation of Insulin Secretion and Diabetes type I pathways." (PMID 29081736, 2017). "Pancreatic islet transplant is an effective treatment for type 1 diabetes (T1D), a disease in which the immune system induces insulin depletion by specifically attacking insulin producing beta cells within pancreatic islets." (PMID 28832685, 2017). "Based on age at diagnosis being <30 y and insulin use, 0.2% of the cases were likely to be type 1 diabetes." (PMID 28399126, 2017). "Despite current advances in the understanding of type 1 diabetes, treatment remains largely limited to insulin replacement therapy and attempts to prevent or cure the disease in humans have so far been unsuccessful." (PMID 28356069, 2017). "Such nano-biosensors can be used to emulate the body’s physiological needs to trigger the delivery of insulin to provide effective therapeutics for type 1 diabetes." (PMID 28469179, 2017). "In Adipose Tissue‐Derived MSCs, insulin‐producing ADSCs were used to treat patients with type I diabetes mellitus with good effect 77, 78, but the relative contributions of ADSCs and bone marrow were difficult to ascertain." (PMID 28191766, 2017). "Type 1 diabetes results from the destruction of pancreatic β-cells, which are responsible for insulin secretion." (PMID 28738076, 2017). "Physical activity improves fasting blood glucose levels and insulin sensitivity in patients with type 1 diabetes (type 1 DM), leading to a reduction in the required daily dose of insulin." (PMID 29259658, 2017). "Type 1 diabetes mellitus (T1D) is the consequence of an autoimmune attack on β-cells that significantly impairs insulin production." (PMID 29112978, 2017). "Type 1 diabetes is an autoimmune disease characterised by the destruction of insulin producing beta cells in the pancreas." (PMID 28770318, 2017). "(2008) reported increased blood glucose levels in a similar animal model of experimental type 1 diabetes, and they found a reduction in the insulin‐producing β‐cells in diabetic rats receiving HBO therapy compared with a control group." (PMID 28336821, 2017). "Recent studies employing highly sensitive C-peptide assays suggest that individuals with long-term type 1 diabetes secrete residual amounts of insulin." (PMID 28550517, 2017).
type 1 diabetes (continued). "With insulin replacement by injection being the only approved therapy for type 1 diabetes, there has seemed little need to identify disease heterogeneity from a clinical–pathological perspective." (PMID 28770323, 2017). "In the case of type 1 diabetes, the hyperglycemia can be efficiently managed by means of insulin supplementation, but patients still display an overall shorter life expectancy and a relatively altered quality of life." (PMID 28634486, 2017). "The present study evaluated the safety and efficacy of closed-loop insulin delivery during unannounced (to the closed-loop algorithm) afternoon physical activity and during the following night in young people with type 1 diabetes." (PMID 28840263, 2017). "Insulin deprivation was shown to decrease mitochondrial ATP production in patients with type 1 diabetes and insulin treatment of human or rat muscle cells in vitro elevated oxygen consumption and respiratory control ratio." (PMID 28556799, 2017). "Transplantation of insulin-producing islet cells has been shown to be an effective treatment for severe type 1 diabetic patients." (PMID 28968432, 2017). "Our data indicate a role for offering CGM to all pregnant women with type 1 diabetes using intensive insulin therapy in the first trimester." (PMID 28923465, 2017). "Thirty-one patients with type 1 diabetes receiving basal-bolus therapy of insulin degludec underwent at-home CGM assessments." (PMID 28683068, 2017). "Continuous subcutaneous insulin infusion (CSII) is an effective tool to improve type 1 diabetes mellitus (T1DM) control, although many patients remain with hemoglobin A1c (HbA1c) levels >7%." (PMID 28004007, 2016). "A disproportionately high PI value, expressed as PI:C or PI:insulin ratio, was proposed to mainly indicate sub(clinical) beta cell dysfunction in (impending) type 2 or type 1 diabetes." (PMID 27907006, 2016). "When beta cells in the pancreas are destroyed and unable to produce, store, and release the hormone insulin, type 1 diabetes(formerly known as insulin-dependent) occurs." (PMID 27535125, 2016). "The novel sodium glucose co-transporter 2 (SGLT2) inhibitor empagliflozin has recently been reported to improve glycemic control in streptozotocin-induced type 1 diabetic rats in an insulin-independent manner, via an increase in urinary glucose output." (PMID 26807719, 2016). "Interruption of insulin supply due to kinking or blockage of the infusion set can lead to the rapid development of extreme hyperglycemia, especially in type 1 diabetes." (PMID 26742082, 2016). "Overall, an increase in intensified insulin therapy is reported in children and adolescents with type 1 diabetes." (PMID 27532627, 2016). "Exogenous insulin is the only treatment available for type 1 diabetic patients and is mostly administered by subcutaneous (SC) injection in a basal and bolus scheme using insulin pens (injection) or pumps (preimplanted SC catheter)." (PMID 27504460, 2016). "Type 1 Diabetes (T1DM) is an autoimmune disease characterized by pancreatic beta cell destruction leading to decreased insulin secretion." (PMID 27777901, 2016). "Type 1 diabetes (T1D) results from autoimmune destruction of the insulin-producing β-cells within the pancreatic islets of Langerhans." (PMID 27009429, 2016). "Insulin infusion is done in hospitalized patients having type 1 diabetes and in type 2 diabetic patients, oral drugs are stopped and insulin is started for glycaemic control." (PMID 28197516, 2016). "From the biochemical background, I-OMe-AG538 makes blocking of the insulin to bind with the receptor and the increased insulin leads to a condition similar to type I diabetes mellitus." (PMID 27579151, 2016). "The traditional treatment for type 1 diabetes and some type 2 and gestational diabetes has been with human insulin." (PMID 27192491, 2016).